FGA (fibrinogen alpha chain)
Diseases named in the same sentence as FGA in open-access papers (continued):
Sharing a sentence is not in itself a finding about the gene and the disease.
Stroke (7 papers, 2014 to 2024). Sudden impairment of blood flow to a part of the brain due to occlusion or rupture of an artery to the brain. "In female patients, 12 of the 34 SVD-associated genes were unique to that stroke cause, including FGA, SLC22A3, both unique to the female cohort, and SLC4A1 which was also expressed in males, though by different exons and junctions." (PMID 33193047, 2020). "Our present findings that CRP and FGA levels were associated with the three ischemic stroke subtypes confirm previous findings in other cohorts of stroke patients." (PMID 31242583, 2019). "If replicated, this would be consistent with modest risk increase for stroke that other variants associated to circulating D-dimer levels, such as reported for variants in coagulation Factor V, Factor III and FGA." (PMID 25078778, 2014).
amyloidosis (6 papers, 2018 to 2025). A disorder characterized by the localized or diffuse accumulation of amyloid protein in various anatomic sites. "AFib amyloidosis leads especially to end-stage kidney disease in the elderly, and the deposit formation is associated with a mutation in the FGA gene." (PMID 36293523, 2022). "The most common variant associated with fibrinogen amyloidosis is FGA p.Glu545Val." (PMID 33807613, 2021). "The mutation of FGA will cause the clinical disorder of amyloidosis in the liver or other tissues." (PMID 32851066, 2020). "Furthermore, the disease-gene associations related to amyloidosis (Apolipoprotein E [APOE], C3, FGA, Transthyretin [TTR], and Serum amyloid P-component [APCS or SAMP]) showed significant enrichment (FDR = 2.66E-5)." (PMID 37875373, 2023). "Specifically, ATTRv amyloidosis are related to the presence of point mutations in the TTR gene including Val30Met, Val122Ile, Thr60Ala, and AFib amyloidosis is caused by point mutations (most common Glu526Val) or frameshift mutations in the FGA gene." (PMID 36293523, 2022). "We were able to additionally type three samples of ALλ (CON7; lymph node (n = 1)), ATTR (CON8; bursa (n = 1)), and ALκ (CON9; myocardium (n = 1)) with unspecific or negative IHC results, but additional high abundance of ApoA4, FGA, and KRT, respectively, without defining the amyloidosis type." (PMID 40701201, 2025).
hepatocellular carcinoma (6 papers, 2018 to 2026). A malignant tumor that arises from hepatocytes. "FGA was identified as a downstream target; in hepatoma cells, FGA protein levels were regulated by miR-4461." (PMID 42062626, 2026). "In summary, these results suggested that FGA expression is lower in hepatocellular carcinoma tissue compared to normal liver tissue." (PMID 39227068, 2024). "Furthermore, using UNCLAN data to evaluate FGA expression levels in hepatocellular carcinoma, we observed that FGA expression was significantly decreased in HCC compared to normal tissue (P < 0.001)." (PMID 39227068, 2024). "We observed that FGA expression was lower in liver carcinoma tissue." (PMID 39227068, 2024). "In conclusion, this study establishes a semi-nested RT-PCR assay to quantify plasma FGA mRNA, demonstrating its utility for hepatocellular carcinoma (HCC) diagnosis." (PMID 40506936, 2025).
bleeding disorders (5 papers, 2014 to 2025). "Congenital fibrinogen disorders (CFDs) are rare bleeding disorders (RBDs) caused by mutations in 1 of the 3 fibrinogen genes (FGA, FGB, and FGG)." (PMID 38953055, 2024). "Congenital fibrinogen deficiencies are rare bleeding disorders, characterized by extensive genetic heterogeneity in all the three genes: FGA, FGB, and FGG (enconding the Aα, Bβ, and γ chain, respectively)." (PMID 32610551, 2020). "Among bleeding disorders, mutations were primarily found in VWF (15%), FGG (15%), F8 (12%), F7 (12%), and FGA (11%)." (PMID 40488813, 2025). "Mutations in three genes (FGA, FGB, FGG) encoding fibrinogen α-, β- and γ-chains lead to congenital fibrinogen deficiency, which is an extremely rare hereditary bleeding disorder, affecting 1 in 1,000,000 individuals." (PMID 25275492, 2014).
colorectal cancer (4 papers, 2018 to 2022). A primary or metastatic malignant neoplasm that affects the colon or rectum. "Fibrinogen alpha chain (FGA) has been reported as a serum peptide signature being a hallmark of a variety of tumors, including colorectal cancer, esophageal squamous cell carcinoma, non-small cell lung cancer, pancreatic ductal adenocarcinoma." (PMID 36338720, 2022).
lung adenocarcinoma (4 papers, 2022 to 2025). A carcinoma that arises from the lung and is characterized by the presence of malignant glandular epithelial cells. "Furthermore, the FGA isoform has been shown to be a predictor of targeted therapy in patients with EGFR-mutated lung adenocarcinoma." (PMID 35463955, 2022).
lung squamous cell carcinoma (4 papers, 2023 to 2025). "For example, FGA, an adverse risk marker in our model, has been shown to predict poor survival in lung squamous cell carcinoma (LUSC), the second common subtype of NSCLC, in multiple patient cohorts." (PMID 37434467, 2023). "The m7G immune-related genes FGA, CSF3R, and ORM1 increase the survival risk in patients with lung squamous cell carcinoma, whereas NTS exerts a protective effect." (PMID 40098956, 2025). "In addition, FGA was found to be under-expressed in bile duct carcinoma, lung squamous cell carcinoma, and kidney chromophobe tissue, while it was overexpressed in colon adenocarcinoma and rectal adenocarcinoma, indicating abnormal FGA expression across multiple types of tumors." (PMID 39227068, 2024). "FGA protein peaks are highly expressed in gastric ADC, Stage I lung squamous cell carcinoma, and colon cancer, as demonstrated by several blood proteomics studies." (PMID 40722683, 2025).
myocardial infarction (4 papers, 2010 to 2023). Gross necrosis of the myocardium, as a result of interruption of the blood supply to the area, as in coronary thrombosis. "Polymorphism in fibrinogen alpha chain (FGA) was liable for progression of myocardial infarction, but this polymorphic gene may be involved in pathogenesis of CAD." (PMID 31881747, 2019).
ovarian carcinoma (4 papers, 2016 to 2024). A malignant neoplasm originating from the surface ovarian epithelium. "Zhang and colleagues identified LBP (lipopolysaccharide-binding protein), GSN (gelsolin), FGA (fibrinogen alpha chain), and FGG (fibrinogen gamma chain) as potential diagnostic exosomal proteins for ovarian cancer, with FGA found to be the most promising diagnostic marker." (PMID 34571921, 2021).
viral infection (4 papers, 2014 to 2025). "In particular, vWF, HRG, PROS1, GC, F2, FGA, and FGB proteins, which are responsible for the expansion of vessels and new vessel formation, modulate blood coagulation and mitigate against vasoconstriction and coagulation caused by virus infection." (PMID 35401544, 2022).
coronary artery disease (3 papers, 2010 to 2023). "FGA polymorphisms are closely associated with adult coronary artery disease, and CAL is the most serious complication of KD." (PMID 37575991, 2023). "The proportion of FGA genotype GA in children with CAL was significantly higher than that in children without CAL, suggesting that FGA gene polymorphisms affect coronary artery disease in children with KD." (PMID 37575991, 2023). "In the present study we used a tagSNP approach to evaluate the role of genetic variation across FGA, FGB and FGG genes in the occurrence of coronary artery disease in a homogeneous Greek population sample of 305 patients and 305 controls." (PMID 20167083, 2010).
endometrial cancer (3 papers, 2024 to 2025). Primary or metastatic malignant neoplasm involving the endometrium (mucous membrane that lines the endometrial cavity). "A 5-biomarker panel of cervico-vaginal fluid derived proteins (HPT, LG3BP, FGA, LY6D and IGHM) predicted endometrial cancer with an AUC of 0.95 (0.91–0.98), sensitivity of 91% (83%–98%), and specificity of 86% (78%–95%)." (PMID 38513301, 2024). "A 5-biomarker signature of cervico-vaginal fluid proteins combining HPT, LG3BP, FGA, LY6D and IGHM predicted endometrial cancer with an AUC of 0.95 (0.91–0.98), sensitivity of 91%, and specificity of 86%." (PMID 38513301, 2024).
endometriosis (3 papers, 2014 to 2022). The growth of functional endometrial tissue in anatomic sites outside the uterine body. "Notably, the top genes associated with Stage B endometriosis in these pathways include FN1, FGG and FGA which are also part of the Reactome integrin linkage to MAPK pathways associated with all endometriosis." (PMID 28333195, 2017). "Our previous work revealed the high expression of fibrinogen alpha chain (FGA) in patients with endometriosis (EM) and that it could promote the migration and invasion of endometrial stromal cells." (PMID 35498401, 2022). "Notably, this includes FN1, FGG and FGA, which are also part of the Reactome MAPK-related pathways associated with all endometriosis." (PMID 28333195, 2017).
ischemic stroke (3 papers, 2019 to 2023). A stroke disorder caused by obstruction of blood flow to the brain, due to thrombotic (local blood clot formation) or embolic (due to a blood clot or other material traveling from another site) event. "For example, some of the differentiation proteins, such as SERPINA3 and CRP involved in inflammatory/acute-phase response, as well as FGA and PLG involved in blood coagulation, were associated with the cardioembolic, large-vessel, and lacunar ischemic stroke subtypes, but not with CBS deficiency." (PMID 31242583, 2019).
metastatic tumors (3 papers, 2015 to 2024). "When FGA was overexpressed, there was a reduction in visible lung metastatic tumors." (PMID 39227068, 2024). "In a mouse model of metastatic tumors, overexpression of FGA restricted the spread of tumor cells." (PMID 39227068, 2024).
anemia (2 papers, 2022 to 2023). A reduction in the number of red blood cells, the amount of hemoglobin, and/or the volume of packed red blood cells. "We further analyzed HBA1 and FGA abundance levels in the peripheral blood as markers for anemia and thromboembolic disease, respectively." (PMID 36759757, 2023).
asthma (2 papers, 2022 to 2023). "SAA1, FGA, SAP, and CETP can be potentially useful biomarkers for early diagnosis of EGPA and differential diagnosis of asthma." (PMID 37215720, 2023). "The combination of SAA1, FGA, SAP, and CETP as biomarkers for differential diagnosis of asthma had an AUC of 0.921, a sensitivity of 78.13%, and a specificity of 100%, which were all larger than single markers." (PMID 35757752, 2022). "We have identified and validated four new potential serum biomarkers, including SAA1, FGA, SAP, and CETP, that can be used to distinguish EGPA from severe asthma." (PMID 35757752, 2022). "In the EGPA vs. asthma analysis, SAA1, FGA, SAP, and CEPT alone had slightly lower sensitivity but still showed good AUC and specificity." (PMID 35757752, 2022). "The serum levels of SAA1, FGA, and SAP in the EGPA group were significantly elevated as compared to the healthy control and severe-asthma groups, while the serum CETP was significantly lower in the EGPA group compared with the severe-asthma group." (PMID 35757752, 2022).
atherosclerosis (2 papers, 2024 to 2025). A disease characterized by the build-up of fatty material and calcium deposition in the arterial wall resulting in partial or complete occlusion of the arterial lumen. "We also found certain HS disaccharides (D0H0) associated with APP and other proteins increased in CAA (OLFML3, FRZB, ApoE, FGA), as well as with ApoE genotype, but not with atherosclerosis." (PMID 40156913, 2025).
colorectal tumors (2 papers, 2021 to 2025). "Comprehensive studies have shown that serum levels of FGA are upregulated in a variety of malignant tumors, including endometrial, hepatocellular, gastric, and colorectal tumors, which is consistent with our findings." (PMID 40098956, 2025).
depression (2 papers, 2021 to 2025). "By studying the differentially expressed proteins of the exogenous coagulation pathway in the plasma samples of depression patients, we found that FGA, FGB, FGG and FVII in the EC pathway have all changed significantly." (PMID 34488523, 2021). "In conclusion, we screened 4 DEPs (FGA, FGB, FGG and FVII) in the EC pathway from depression patients’ plasma and provided potential biomarkers for the diagnosis of depression." (PMID 34488523, 2021).
diabetes (2 papers, 2023 to 2025). "Studies have also shown the association of the FGA gene with different types of diabetes, including T2D, type 1 diabetes, diabetic neuropathy, and gestational diabetes." (PMID 39747296, 2025).
hypodysfibrinogenemia (2 papers, 2021 to 2024). "Our study reported 3 patients with hypodysfibrinogenemia from the same family who had 3 compound missense mutations in the FGA, FGB, and FGG genes." (PMID 38953055, 2024).
insomnia (2 papers, 2021 to 2022). A sleep disorder characterized by difficulty in falling asleep and/or remaining asleep. "In the results, HP, FGA, FGG, FGB, and MMP9 were upregulated in patients with insomnia, and FN1, APP, EGF, AHSG, and IGF1 were downregulated compared with controls." (PMID 35958162, 2022). "Among them, HP, MMP9, FGA, FGB, and FGG were validated as upregulated, and APP, AHSG, and IGF1 were downregulated in patients with insomnia." (PMID 35958162, 2022). "Among them, the expression of F2, HP, FGA, FGB, FGG, and ApoB were upregulated in insomnia patients with wakefulness, and A2M, AHSG, APP, and ApoA1 were downregulated." (PMID 33511209, 2021). "On the other hand, through Western blot experiments, we verified that the expression of FGG, FGB, FGA, APOB, F2, and HP was upregulated in insomnia patients with wakefulness compared with the control, while the expression of A2M, AHSG, and APOA1 was downregulated." (PMID 33511209, 2021).
leukemia (2 papers, 2014 to 2021). A malignant (clonal) hematologic disorder, involving hematopoietic stem cells and characterized by the presence of primitive or atypical myeloid or lymphoid cells in the bone marrow and the blood. "The levels of FGA and GSTP1 protein differed among the leukemia cells in distinct ALL groups and normal cells by immunoblotting." (PMID 25317080, 2014).
prostate carcinoma (2 papers, 2015 to 2022). A carcinoma that arises from epithelial cells of the prostate gland. "A proteomic analysis of the urine revealed APPs (FGA, FGG, HP, ITI4, SERPINA1) as biomarkers for prostate cancer, but the paper lacks the analysis of their pathophysiological role." (PMID 35328392, 2022).
Renal amyloidosis (2 papers, 2023). A form of amyloidosis that affects the kidney. "In addition, mutations in FGA are associated with fibrinogen A α-chain amyloidosis, a type of hereditary renal amyloidosis." (PMID 37784196, 2023).
renal cell carcinoma (2 papers, 2015 to 2019). "Some of the proteins such as SERPINA1, FGG, FGA, APOA1 and HP were also found with differential abundance in urine in proteomics studies of bladder cancer, and TYMP in tissue in renal cell carcinoma, but mostly with opposite abundance level compared to our study." (PMID 25653573, 2015).
systemic lupus erythematosus (2 papers, 2019 to 2021). An autoimmune multi-organ disease typically associated with vasculopathy and autoantibody production. "SERPING1, C3, FGA, FGG, and CFH were significantly related to autoimmune diseases, and C3 in particular is associated with systemic lupus erythematosus (SLE) that shows a similar immunopathogenic basis to pSS." (PMID 34516718, 2021). "C3, CFH, SERPING1, FGA, and FGG were significantly enriched in the “complex and coagulation cascades pathway,” C3 was also enriched in the “systemic lupus erythematosus” pathway, and PRB1 in the “salivary secretion” pathway." (PMID 34516718, 2021).
African trypanosomiasis (1 paper, 2023). "FGA is a structural component of the extracellular matrix, while ALB is involved in oxygen binding; IL10 in African trypanosomiasis signaling and the malaria signaling pathway, and REN in the renin angiotensin system signaling pathway." (PMID 36762194, 2023).
allergic rhinitis (1 paper, 2025). Inflammation of the nasal mucous membranes caused by an IgE-mediated response to external allergens. "The proteins ORM, APOH, FGA, CTSD, and SERPINB3, which showed promise in preclinical studies for predicting response to glucocorticoids, have also been evaluated in clinical trials involving patients with seasonal allergic rhinitis (SAR)." (PMID 40551926, 2025).
babesiosis (1 paper, 2023). Babesiosis refers to a condition caused by microscopic parasites that infect the red blood cells. "Other identified proteins that differentiated uncomplicated from complicated babesiosis were various complement cascade components (CFI, CFP, C2, SERPING1, C8G), extracellular matrix components (TGFBI), acute phase proteins (ORM1, ITIH2, ITIH4, FGA, TF, RBP4) and lipoproteins (apoE)." (PMID 37353646, 2023).
chronic hepatitis (1 paper, 2024). An active inflammatory process affecting the liver for more than six months. "FGA has been shown to be a serological marker for chronic hepatitis, in which expression of the 5.9 kDa fragment of the FGA C-chain was inhibited." (PMID 39227068, 2024).
chronic thromboembolic pulmonary hypertension (1 paper, 2025). Chronic thromboembolic pulmonary hypertension (CTEPH) is characterized by the persistence of thromboemboli in the form of organized tissue obstructing the pulmonary arteries. "Our reference panel shows an insertion of 28 bp at chr4:154584089 (dbSNP: rs148317511; ClinVar: RCV000247066) in a high linkage (phased r = 0.98) with rs6050-C, a missense mutation in FGA associated with venous thromboembolism and chronic thromboembolic pulmonary hypertension." (PMID 41041811, 2025).
coagulation disorders (1 paper, 2021). "In comparison, it has been shown for at least one patient with Zika diagnosis that the infection can lead to severe liver injury and coagulation disorders with altered blood levels of FGA and other fibrinogens." (PMID 33582300, 2021).
epilepsy (1 paper, 2020). A brain disorder characterized by episodes of abnormally increased neuronal discharge resulting in transient episodes of sensory or motor neurological dysfunction, or psychic dysfunction. "Fibrinogen (FGG, FGA) was also found to be increased in the plasma of patients with epilepsy." (PMID 33082886, 2020).
gingivitis (1 paper, 2013). A disorder involving inflammation of the gums; may affect surrounding and supporting structures of the teeth. "Myosin-9 and fibrinogen alpha chain were detected only in the resolution phase of experimental gingivitis, while histone H1.5 was detected in relative high frequency in both phases (induction and resolution)." (PMID 24098404, 2013).
Immunodeficiency (1 paper, 2016). Failure of the immune system to protect the body adequately from infection, due to the absence or insufficiency of some component process or substance. "With respect to the immune response, up-regulated proteins (like FGA) were pro-inflammatory, while down-regulated proteins participated in antigen processing and antigen presenting (like MYO1G), immunoglobulin and cathelicidin production (like fowlicidin-2), and immunodeficiency (like PTPRC)." (PMID 27761697, 2016).
invasive ductal carcinomas (1 paper, 2022). "Alterations in the FGA locus have been detected in invasive ductal carcinomas, highlighting the importance of this chromosomal region." (PMID 35456396, 2022).
mastitis (1 paper, 2022). Inflammation of breast tissue during lactation or postpartum due to an obstructed duct or infection. "Proteins that stand out as logical candidates for further analyses include various APPs and vascular-derived proteins such as C3, C4, TF, ALB, TTR, FGA, and ITIH4 in mastitis whey of E. coli infected cows by 2-DE and label-free methods, respectively." (PMID 36335251, 2022).
nasal polyp (1 paper, 2021). "Coagulation proteins FGA, FGB, FGG, and fibronectin (FN1) were all also abundant in nasal polyp biopsies in this study." (PMID 33220024, 2021).